TOPBP1 (DNA topoisomerase II binding protein 1)
Diseases named in the same sentence as TOPBP1 in open-access papers (continued):
Sharing a sentence is not in itself a finding about the gene and the disease.
ovarian carcinoma (7 papers, 2012 to 2025). A malignant neoplasm originating from the surface ovarian epithelium. "The BET bromodomain inhibitor JQ1 synergized with the PARP inhibitor olaparib in BRCA1/2 wild-type ovarian cancer both in vitro and in vivo and was correlated with the suppression of both TOPBP1 and WEE1." (PMID 36139634, 2022). "It was previously reported that JQ1 synergized with olaparib in BRCA1/2 wild-type ovarian cancer both in vitro and in vivo and correlated with the suppression of TOPBP1 and WEE1." (PMID 36139634, 2022). "In another study, the upregulation of Polθ and its positive correlation with expression of many DNA repair genes including TOPBP1, BLM, RAD54L, FANCI, BRCA1, FANCD2, ATAD5 was reported in HR-deficient epithelial ovarian cancer cells." (PMID 34762643, 2021).
prostate carcinoma (7 papers, 2015 to 2025). A carcinoma that arises from epithelial cells of the prostate gland. "Indeed, high TopBP1 expression is associated with more SCNA in prostate cancer." (PMID 33556369, 2021). "Quinacrine and thimerosal inhibited SN-38-induced TopBP1 focus formation also in the prostate cancer cell line LNCaP." (PMID 41190242, 2025). "A transcriptional role for MYCN in upregulating the DDR has been given further credence by the recent identification of MYCN binding sites in the promoters of PARP1, PARP2, BRCA1, RMI2, and TOPBP1, albeit in castration resistant prostate cancer." (PMID 32577161, 2020). "To investigate the effect of TopBP1 on the proliferation abilities of prostate cancer cells, we knocked down the expression of TopBP1 in LNCaP and 22RV1 cells." (PMID 32459662, 2020). "Inherent in our findings is the implication that TopBP1 is a predictor for PCa prognosis and it may prevent prostate cancer from the accumulation of DNA damages via ATR-Chk1 signaling pathway." (PMID 32459662, 2020). "Furthermore, TopBP1-involved c-myb regulated DDR pathway was proposed by recent studies on castration-resistant prostate cancer." (PMID 26131719, 2015). "Targeting CDC6 together with Chk1/2 inhibitor could suppress TopBP1-ATR-Chk1 signaling and increase phosphorylation of ATM, a biomarker of DNA damage, synergistically increasing the treatment efficacy in prostate cancer cells." (PMID 32792963, 2020).
lung carcinoma (5 papers, 2014 to 2025). "Depletion of TopBP1 or Claspin using shRNA showed an enhancement of sensitivity to radiation in radioresistant lung cancer cells (PC14PE6)." (PMID 25216549, 2014). "Consistently, depletion of TopBP1 or Claspin in lung cancer cells showed an enhancement of sensitivity to radiation." (PMID 25216549, 2014).
colon cancer (4 papers, 2017 to 2025). "In the present study, we demonstrated that HGF moderately activated Chk1 phosphorylation in colon cancer cells by upregulating TopBP1 and RAD51, and promoting TopBP1–ATR complex formation." (PMID 28573382, 2017). "Finally, we explored the association of AKT activity with TopBP1 and RAD51 expression in colon cancer cells." (PMID 28573382, 2017). "Our data indicate that the abundance of TopBP1 and BRCA1 correlates with Claspin, Timeless, and CHK1 in colon cancer cell lines, which would be consistent with the latter hypothesis." (PMID 30796221, 2019).
breast tumor (3 papers, 2012 to 2025). "We identified auranofin as an effective inhibitor of TOPBP1 and it elicits a synthetic vulnerability of breast tumor to PARP inhibitors by challenging replication integrity." (PMID 41392982, 2025). "As both CK2 and TOPBP1 have been implicated in breast tumorigenesis, we then aimed to evaluate the role of CK2–HTATSF1–TOPBP1 axis in breast tumor." (PMID 38762174, 2024). "We then analyzed the level of HTATSF1 pS748, which is a functional readout of CK2 activity and is interpreted by TOPBP1, via immunohistochemistry (IHC) in breast tumor tissue and tumor-adjacent normal breast tissue." (PMID 38762174, 2024). "Aberrant expression of TOPBP1 has been observed in multiple malignancies, including breast, ovarian, lung, and colorectal tumors, and high TOPBP1 expression is correlated with poor prognosis and breast tumor aggressiveness, suggesting its potential as a tumor-promoting or prognostic marker." (PMID 41392982, 2025).
Fanconi anemia (3 papers, 2019 to 2025). Fanconi anemia (FA) is a hereditary DNA repair disorder characterized by progressive pancytopenia with bone marrow failure, variable congenital malformations and predisposition to develop hematological or solid tumors. "The activation of this checkpoint requires the relocalization into nuclear foci and the stepwise activation of proteins of the ATR-Chk1 and the Fanconi Anemia (FA) pathways, including Topoisomerase II Binding Protein 1 (TopBP1) and FANCD2." (PMID 31320994, 2019). "We also show that in absence of a functional Dicer or Drosha, the assembly into nuclear foci of the Fanconi anemia (FA) protein FANCD2 and of the replication and checkpoint factor TopBP1 in response to replication stress is impaired, and the activation of the S-phase checkpoint is defective." (PMID 31320994, 2019).
Hereditary breast cancer (3 papers, 2012 to 2014). Breast carcinoma that has developed in relatives of patients with history of breast carcinoma. "Our findings suggested that increased level of TopBP1 protein might be associated with progression of hereditary breast cancer." (PMID 24346708, 2014). "Our data suggest that decreased level of TopBP1 mRNA and increased level of TopBP1 protein might be associated with progression of hereditary breast cancer." (PMID 22544570, 2012). "The results of our earlier studies concerning expression of TopBP1 in hereditary breast cancer showed lower TopBP1 mRNA expression in lobular carcinoma compared with ductal carcinoma." (PMID 23277395, 2013).
osteosarcoma (3 papers, 2018 to 2022). A usually aggressive malignant bone-forming mesenchymal neoplasm, predominantly affecting adolescents and young adults. "Using a DNA fiber assay and human osteosarcoma (U2OS) cell lines inducibly expressing either wild-type or mutant TopBP1, we investigated how an AAD mutant of TopBP1 affects the initiation of DNA replication during the S phase." (PMID 30104465, 2018). "Since treacle recruits TOPBP1 in the DDR process and the latter confers radioresistance in osteosarcoma, TOPBP1 might mediate the effect of treacle on sensitivity to radiotherapy." (PMID 35093935, 2022).
ductal carcinoma (2 papers, 2012 to 2013). "Fifteen of 28 (53.6 %) lobular carcinoma demonstrated detectable mRNA for TopBP1 gene, while the expression of TopBP1 mRNA was observed in 76 of 99 (78.3 %) ductal carcinoma." (PMID 22544570, 2012). "Expression of TopBP1 mRNA was found to be significantly decreased in the lobular carcinoma compared to the ductal carcinoma (p < 0.05)." (PMID 22544570, 2012). "Expression of TopBP1 mRNA in lobular carcinoma was significantly lower compared with ductal carcinoma (p < 0.05)." (PMID 22544570, 2012). "Moreover, expression of TopBP1 mRNA was significantly down-regulated in the lobular carcinoma compared to the ductal carcinoma." (PMID 22544570, 2012).
pancreatic cancer (2 papers, 2018 to 2025). "Collectively, these results demonstrated that in a subcutaneously implanted xenograft mouse model, olaparib effectively suppressed the growth of pancreatic cancer cells following Topbp1 knockdown in Patu8988 cells characterized by high Topbp1 expression." (PMID 39920847, 2025). "Utilizing TCGA data, our clinical samples, and pancreatic cell lines, we confirmed the overexpression of TOPBP1 in pancreatic cancer cells and tissues." (PMID 39920847, 2025). "Through co-immunoprecipitation, we observed an interaction between PARP1 and TOPBP1 in pancreatic cancer cell lines, indicating the involvement of complex molecular regulatory mechanisms in the combined effects of olaparib with shTOPBP1 or ATRi." (PMID 39920847, 2025). "Three commercially available TOPBP1-knockdown pancreatic cancer cell lines, namely Patu8988, PANC1, and BXPC3, were treated with olaparib." (PMID 39920847, 2025). "Hence, pancreatic tumor cells expressing high levels of TOPBP1 may exhibit heightened sensitivity to olaparib, leading to an exacerbation of the ATM pathway burden." (PMID 39920847, 2025). "However, further investigation is necessary to elucidate the complex role of TOPBP1 in the etiology and DDR of pancreatic cancer, as well as its clinical significance." (PMID 39920847, 2025). "Additionally, we evaluated the baseline TOPBP1 expression levels in PDAC cell lines, finding higher levels in pancreatic cancer cell lines than in normal pancreatic cell lines." (PMID 39920847, 2025). "Interestingly, truncation mutations of RHNO1 that eliminate the region of the protein in which this putative phosphorylation site occurs, and which are therefore unlikely to be unable to bind TOPBP1, have been identified in a number of families with hereditary pancreatic cancer." (PMID 30295604, 2018).
Bloom syndrome (1 paper, 2015). Bloom syndrome (BSyn) is a rare chromosomal breakage syndrome characterized by a marked genetic instability associated with pre- and postnatal growth retardation, facial sun-sensitive telangiectatic erythema, increased susceptibility to infections, and predisposition to cancer. "Finally, given that cells expressing mutant BLM that cannot bind TopBP1 display increased SCEs and chromosomal aberrations, our data may have important implications for understanding the increased cancer susceptibility and pathologies observed in Bloom syndrome patients." (PMID 25794620, 2015).
endometrial cancer (1 paper, 2014). Primary or metastatic malignant neoplasm involving the endometrium (mucous membrane that lines the endometrial cavity). "In conclusion, our results showed that rs115160714 is associated with increased expression of TopBP1 and endometrial cancer risk." (PMID 24346708, 2014). "In this study, we demonstrated that out of five studied polymorphisms in the 3′UTR region of TopBP1 gene only one, the rs115160714 was significantly associated with endometrial cancer risk." (PMID 24346708, 2014). "We examined the association between five single nucleotide polymorphisms (rs185903567, rs116645643, rs115160714, rs116195487, and rs112843513) located in the 3′UTR region of the TopBP1 gene and endometrial cancer risk as well as allele-specific gene expression." (PMID 24346708, 2014). "The results of our study raise a possibility that a genetic variation of TopBP1 may be implicated in the etiology of endometrial cancer." (PMID 24346708, 2014). "In present study we tested the effect of five SNPs [rs185903567 (G/A), rs116645643 (A/G), rs115160714 (C/T), rs116195487 (C/G), and rs112843513 (C/delC)] in the 3′UTR (3′untranslated region) of TopBP1 gene on endometrial cancer risk as well as on allele-specific mRNA/protein expression." (PMID 24346708, 2014). "In this study we investigated whether alterations in the TopBP1 gene can influence the risk of endometrial cancer." (PMID 24346708, 2014). "The biological functions of TopBP1 protein as well as its close similarity with BRCA1 prompted us to investigate whether alterations in TopBP1 gene can influence the risk of endometrial cancer." (PMID 24346708, 2014). "We found TopBP1 protein expression in 81.2 %, 75.0 % and 0.0 % of endometrial cancer tissue homogenate samples of CC, CT, and TT genotype carriers, respectively." (PMID 24346708, 2014).
lung squamous cell carcinomas (1 paper, 2015). "ATR, ATRIP and TOPBP1 are altered in 45/212 lung squamous cell carcinomas (21 %) in the TCGA database." (PMID 26438152, 2015).
lymph node metastasis (1 paper, 2020). "By using both clinicopathological data of TCGA and TMA, the present study revealed that TopBP1 expression had positive correlation with Gleason score, clinical stage, distant and lymph node metastasis." (PMID 32459662, 2020).
lymphoma (1 paper, 2022). A malignant (clonal) proliferation of B- lymphocytes or T- lymphocytes which involves the lymph nodes, bone marrow and/or extranodal sites. "This experiment, originally performed before our RNA Seq and proteomic analysis of reimplanted Eμ-Myc lymphomas was completed, revealed lower levels of Claspin mRNA and protein expression in primary RelA T505A Eμ-Myc lymphomas, while ATR, CHK1, ATRIP, RAD17 and TOPBP1 were unaffected." (PMID 36240065, 2022).
pulmonary fibrosis (1 paper, 2025). Chronic progressive interstitial lung disorder characterized by the replacement of the lung tissue by connective tissue, leading to progressive dyspnea, respiratory failure, or right heart failure. "For example, YTHDC1 has been reported to mitigate cellular senescence-induced pulmonary fibrosis by facilitating the interaction between DNA topoisomerase 2-binding protein 1 (TopBP1) and Meiotic Recombination 11 (MRE11), thereby enhancing DNA damage repair." (PMID 39756462, 2025).
rheumatoid arthritis (1 paper, 2025). A chronic, systemic autoimmune disorder characterized by inflammation in the synovial membranes and articular surfaces. "In this study, we identified auranofin, an FDA-approved anti–rheumatoid arthritis agent, as a TOPBP1 inhibitor with high potency in disrupting the interaction of TOPBP1 with PHF8 and FANCJ by docking to the hydrophobic pocket of BRCT 7–8." (PMID 41392982, 2025). "Here, we identify auranofin, the FDA-approved drug for rheumatoid arthritis, as a lead compound capable of binding to the BRCT 7–8 domains and blocking TOPBP1 interaction with PHF8 and FANCJ." (PMID 41392982, 2025).
Treacher-Collins syndrome (1 paper, 2019). A congenital disorder of craniofacial development characterized by bilateral symmetrical oto-mandibular dysplasia without abnormalities of the extremities, and associated with several head and neck defects. "Unexpectedly, we found that Treacle, a nucleolar factor mutated in Treacher Collins syndrome, is needed for TopBP1 retention in nucleoli under hypoosmotic stress conditions." (PMID 31114877, 2019).
uterine corpus endometrioid carcinoma (1 paper, 2021). "In TCGA uterine corpus endometrioid carcinoma, high levels of TopBP1 are also significantly found in cluster 4, which is characterized by a very high degree of SCNAs." (PMID 33556369, 2021).
cancer (40 papers, 2007 to 2025). A tumor composed of atypical neoplastic, often pleomorphic cells that invade other tissues. "Our findings indicate that higher levels of SEC31A1 are positively associated with increased IC50 values of cancer therapy drugs, whereas the expression of TOPBP1, ESPL1, and CPSF3 displayed an opposite correlation." (PMID 37417208, 2023). "To obtain further evidence for the association between high TopBP1 expression and genome instability in cancer, we explored several cancer genome databases." (PMID 33556369, 2021). "The clinical significance of these findings is supported by an association between TopBP1 overexpression and genome instability in many types of human cancer." (PMID 33556369, 2021). "In fact, high levels of TopBP1 expression are strongly associated with genome instability in many types of cancer." (PMID 33556369, 2021). "To uncover novel proteins potentially involved in DNA repair and cancer predisposition, we screened for TOPBP1 interactors using the yeast two-hybrid system." (PMID 29511213, 2018). "Thus, the levels of TopBP1 that can cause a paradoxically inhibitory effect on Chk1 activation are within the physiological range seen in many cancer cells." (PMID 33556369, 2021). "We do not know what could make TopBP1 more stable but it can be associated with TopBP1 mislocalization in cancer cells." (PMID 22544570, 2012). "Thus, beyond ATR signaling, disruption of TopBP1 compartmentalization by quinacrine may inhibit additional TopBP1-associated functions that determine the capacity of cancer cells to process DNA lesions in coordination with cell cycle progression." (PMID 41190242, 2025). "Notably, TOPBP1 has also been associated with tumorigenesis in multiple cancer types." (PMID 39920847, 2025). "Indeed, TopBP1 overexpression is associated with genome instability in many types of cancer." (PMID 33556369, 2021). "Thus, increased expression of TopBP1 may cause deregulation of this important tumor suppressor protein and contribute to cancer development or progression." (PMID 24346708, 2014). "The dissociation of PHF8 from TopBP1 presents a potential strategy for developing novel cancer therapies targeting TopBP1." (PMID 41198671, 2025). "Previous studies have shown that inhibiting TOPBP1 expression or activity can sensitize cancer cells to chemotherapy and radiation therapy." (PMID 39920847, 2025). "In PDAC cancer cell lines, we evaluated the abundances of TOPBP1, p-ATR, p-ATM, p-CHK1, and p-CHK2 proteins—key genes in the ATR and ATM pathways." (PMID 39920847, 2025). "DNA topoisomerase II-binding protein 1 (TOPBP1) plays a supportive role in regulating the DDR pathway, and its overexpression has been linked to the tumorigenesis of various cancers." (PMID 39920847, 2025). "Disruption of TOPBP1 in these cancer cells results in increased sensitivity to radiation or PARPi, and mutation of TOPBP1 in clinical tumor samples impairs its ability to recruit to and repair of DNA lesions." (PMID 38762174, 2024). "To gain insight into how Chk1 disrupts the Treslin–TopBP1 interaction, we undertook a comprehensive analysis of the dissociation of the proteins in cancer cell line models." (PMID 35231445, 2022). "In contrast, moderate depletion of TopBP1 by shRNA in TopBP1-overexpressing cancer cells enhanced ATR/Chk1 activation and S-phase checkpoint response after replicative stress." (PMID 33556369, 2021).